ACHE (acetylcholinesterase (Yt blood group))
Diseases named in the same sentence as ACHE in open-access papers (continued):
Sharing a sentence is not in itself a finding about the gene and the disease.
cancer (continued). "This review focuses on analyzing the involvement of AChE during cancer progression and proposes AChE as a central regulator in the initiation and progression of cancer via the cholinergic system." (PMID 37760598, 2023). "All this indicates that the expression of AChE in tumors depends on the tumor origin and probably the cancer stage." (PMID 37760598, 2023). "In recent years, the role of AChE in the initiation and development of cancer has been extensively studied." (PMID 37760598, 2023). "These various biological effects only confirm that there is a very fine line between the AChEIs via modulating AChE activity that has acted as a suppressor of cancer cell proliferation or conversely as an initiator of cancer cell proliferation." (PMID 33917200, 2021). "AChE is expressed not only in the brain but also in epithelial, endothelial, immune, and cancer cells." (PMID 34073579, 2021). "The anti-proliferative effect of these compounds, which were originally designed for AChE inhibition, led us to further study their utility in cancer therapeutics." (PMID 34500749, 2021). "Inhibition of COX-2 and AChE is a desirable feature of an anti-cancer drug considering the role of these enzymes in cancer cell progression and metastasis." (PMID 34500749, 2021). "Considerable pharmacological experiments in vitro have demonstrated that AH possessed anti-neuroinflammatory, anti-adipogenic, anti-inflammatory, antibacterial, anti-cancer, anti-oxidation, anti-AChE, anti-BuChE, and antihyaluronidase activities." (PMID 33921386, 2021). "There is a need for the identification of newer generation AChE inhibitors that have additional properties including anti-cancer activity." (PMID 34500749, 2021). "These pyrrolidine-spirooxindole molecules in particular have shown a panoply of significant pharmaceutical targets and applications, such as MDM2 inhibitors, anti-cancer treatment, AChE inhibitors and prospective activity against SARS-CoV-2." (PMID 34885853, 2021). "Knockdown or inactivation of AChE in normal cells decreased while induction of AChE in certain cancer cells increased their sensitivity to apoptotic stimuli." (PMID 32761307, 2020). "In line with these previous studies, in the current study, we were able to demonstrate a cancer-cell-suppressive effect of AChE inhibition and thus indirect cholinergic activation in vitro and in vivo." (PMID 33357230, 2020). "We measured the biological properties, including antioxidant capacity, inhibitory activities against human BACE1, and AChE, and antiproliferative activities toward five cancer cell lines, of the 18 EBPs." (PMID 32711521, 2020). "Our data confirmed that extracts from Selaginella species exhibited cytotoxicity against cancer cell lines and AChE inhibition." (PMID 33375355, 2020). "Human PCa specimens (n = 39) were analyzed for the impact of cancer AChE expression on tumor stage and survival." (PMID 33357230, 2020). "For the first time, Amaryllidaceae alkaloids, metabolites with important biological activities, including anti-cancer, anti-viral, anti-parasitic, and acetylcholinesterase (AChE) inhibitory activity, were detected in apples." (PMID 32317684, 2020). "The results here reported demonstrate novel biological properties of LPE that are able to prevent IL-6-induced invasiveness, to reduced IL-6-stimulated MMP-9/2 up-regulation in gastric MKN-28 and AGS cancer cell lines, and to inhibit in vitro AChE activity." (PMID 31817563, 2019). "On the other hand, bis-thiazoles derived from disubstituted thioureas are supposed to be involved in the regulation of the expression of acetylcholinesterase (AChE) and butyrylcholinesterase (BuChE), overexpressed in pathological conditions; e.g., cancer." (PMID 30248936, 2018). "Its anti-bacterial, anti-malarial, anti-cancer, anti-inflammation, anti-oxidant, anti-fever, alcohol detoxification, and acetylcholine esterase (AChE) inhibitory properties have been witnessed." (PMID 29062800, 2017).
cancer (continued). "The same extract also revealed the strongest effects in anti-cholinesterase and cytotoxic tests at the concentration of 100 μg/mL, AChE enzyme inhibition was 58.55% and human cancer cells, SNU-1 and Hep G2 inhibition was 68.52% and 47.82%, respectively." (PMID 28152649, 2017). "Over the last 45 years a link between cancer cell proliferation and acetycholinesterase (AChE) has become increasingly well established." (PMID 28077796, 2017). "Cinnamyl alcohol, a metabolite of cinnamaldehyde, abundantly exists in Cinnamon Bark and reportedly has inhibitory effects on AChE activity and cancer cell growth." (PMID 26939918, 2016). "A comparison of the changing levels of AChE and BChE mRNAs in carcinomas according to their anatomical location also showed differences." (PMID 25956553, 2015). "We reported here that overexpression of human AChE protein mediated by oncolytic adenovirus suppressed cancer cell growth." (PMID 25220382, 2014). "Additional work will be required to explore the anti-angiogenesis function of AChE in cancer therapy." (PMID 25220382, 2014). "Critical proliferation pathways including PI3K/Akt pathway in cancer cells were inhibited by AChE overexpression." (PMID 25220382, 2014). "Moreover, ACHE activity is increased in various primary tumor tissues and in the serum of some cancer patients." (PMID 40313243, 2025). "The authors suggested that a decrease in cholinesterase levels could lead to elevated AChE concentrations, which might trigger excessive cholinergic stimulation and contribute to increased cancer cell growth." (PMID 40678419, 2025). "Our study has the strength of providing impaired (AChE) activity in cancer patients." (PMID 38429330, 2024). "Our speculation for some relation between impaired (AChE), cancer, and AD might shed light on the puzzling question of why individuals who have had cancer or go on to develop it perform better on memory testing than those who remain cancer-free." (PMID 38429330, 2024). "Moreover, they modulated the cholinesterase activityor expression of ACHE in a cancer cell line-specificmanner, and compound 10 significantly inhibited the cholinesteraseactivity in zebrafish." (PMID 39035947, 2024). "They observed a correlation and involvement of (AChE) in cancer, their study also revealed increased availability of acetylcholine in the neoplastic lung resulting from the fall of cholinesterase activity enhancing cholinergic signaling and contributing to tumor progression." (PMID 38429330, 2024). "The objective is to find a relationship between ACh and AChE and their role in cancer progression." (PMID 37760598, 2023). "The biological activities of the 20 flavones tested herein demonstrated the important role of hydroxyl group positions and numbers in improving their inhibitory activities (antioxidant, anti-SOD, anti-XOD, anti-AChE, anti-inflammatory, and anti-cancer activities against different cancer cell lines)." (PMID 36985391, 2023). "It was demonstrated that AChE activity has essential participation in cancer." (PMID 37760598, 2023). "Modulating ACh levels with AChE could regulate AChRs differentially, thus driving diverse cancer events." (PMID 37760598, 2023). "These events are related to poor prognosis in cancer; therefore, the high AChE activity could favor an environment that is positive for cancer development and promotes metastasis." (PMID 37760598, 2023). "Moreover, the survival analysis in the TCGA data set of cancer patients revealed that a low ACHE expression correlated with a poor outcome." (PMID 37760598, 2023). "Could there be a relationship between the molecular forms of AChE and the regulation of proliferation and apoptosis in cancer?" (PMID 37760598, 2023). "Previously, we analyzed a relationship between high levels of ACh and low levels of AChE activity and how this balance participates in cancer progression and aggressiveness because the ACh induces cell proliferation, inhibition of apoptosis, invasion, and migration." (PMID 37760598, 2023).
cancer (continued). "Although these findings were found in different cancer types and tumoral stages, it led us to formulate a hypothesis involving AChE from tumor initiation to progression to metastasis." (PMID 37760598, 2023). "Comparison between biological activities and electrochemical parameters showed that the first wave reduction potential is an important parameter as follows: the most easily reduced naphthoquinones (>Epc) were the most active against the HepG2 cancer cell lines and as AChE inhibitors." (PMID 36770899, 2023). "According to its traditional efficacies, researchers have conducted a series of studies and found that the plant also possesses anti-neuroinflammatory, anti-adipogenic, anti-inflammatory, antibacterial, anti-cancer, anti-oxidation, anti-AChE, anti-BuChE, and antihyaluronidase functions." (PMID 33921386, 2021). "Amaryllidaceae alkaloids, in particular, have a wide range of biological activities, including anti-cancer, anti-viral, anti-parasitic, and acetylcholinesterase (AChE) inhibitory activity, the latter playing a crucial role in the treatment of Alzheimer’s disease." (PMID 32317684, 2020). "We discovered a strong expression of AChE in cancer cells of human PCa specimens." (PMID 33357230, 2020). "Next, we sought to explore the effect of AChE inhibition on cancer cell growth." (PMID 33357230, 2020). "Additionally, we verified by Western blotting that the studied cancer cell lines exhibited AChE protein expression." (PMID 29371671, 2018). "AChE and BChE activity was measured in serum from cancer patients and in age-matched control group." (PMID 25956553, 2015). "We noticed that Ad.AChE inhibited cancer cell growth at a high MOI level." (PMID 25220382, 2014). "The function of AChE on cancer stem cells will be further validated in vivo." (PMID 25220382, 2014). "Aberration of AChE activity in various types of cancers was reported." (PMID 25220382, 2014). "It was reported that AChE protein participated in apoptosis, and we sought to test whether ZD55-AChE induces cancer cell apoptosis." (PMID 25220382, 2014). "Abnormal expression of AChE protein was found in several types of cancer." (PMID 25220382, 2014). "The intracellular level of ACh were measured in various types of cells to get to know whether it related to the response of cancer cells to AChE overexpression." (PMID 25220382, 2014). "Also, other acetylcholinesterase (AChE) inhibitors were also found, such as the prescription drugs galantamine and huperzine A, the potential AChE inhibitor evodiamine, currently being studied for its anti-cancer properties, and the psychoactive compound mitragynine." (PMID 40558871, 2025). "AChE may function as a potential biomarker for cancer diagnosis or prognosis." (PMID 38429330, 2024). "However, in these tumors, high AChE activity is related to cancer progression and aggressiveness." (PMID 37760598, 2023). "This could leave clear the relevant participation of the AChE in cancer." (PMID 37760598, 2023). "Among pan-cancers, ACHE could be treated as specific prognostic biomarker for KIRC and THCA." (PMID 36825082, 2023). "Furthermore, the AChE might play a key role in cancer cell migration through a pathway common to both neurodegeneration and carcinogenesis." (PMID 36500605, 2022). "Thus, molecular mechanisms of action of the small molecules on non-catalytic function of AChE in lung and other cancer associated with increased level of AChE are the interesting subject of further studies." (PMID 33917200, 2021). "These indicate that AChE might serve as a potential therapeutic target in cancer therapy." (PMID 32503288, 2020). "However, the high MOI request limited Ad.AChE to be further used in cancer therapy." (PMID 25220382, 2014). "S-AgNPs showed strong cytotoxicity against human hepato-cellular carcinoma cells (HepG2) and high enzyme inhibitory effect (IC50 values 27.5μg/ml for AChE and 22.60 μg/ml for BChE) compared to R-AgNPs and RS-AgNPs." (PMID 37014921, 2023).
cancer (continued). "In vitro, antioxidant, inhibition of 15-LOX, AChE, XOD, and cytotoxic (against human cancer lines of IGROV and OVCAR) biological activities of the extracts of this plant were studied for the first time." (PMID 35669910, 2022). "To detect the potential cancer therapeutic function of AChE, we constructed an oncolytic adenovirus carrying AChE gene (ZD55-AChE)." (PMID 25220382, 2014). "Therefore, introduction of the AChE protein back may lead to the growth inhibition of cancer cells." (PMID 25220382, 2014). "The antioxidant potentials of the optimized extracts were evaluated using DPPH, FRAP, TAS, TOS, and OSI parameters; anticholinesterase activities were measured against AChE and BChE enzymes; and antiproliferative activities were investigated in A549, MCF-7, and DU-145 human cancer cell lines." (PMID 40871471, 2025). "The study reported severe impairment in the activity of the (AChE) in all patients with cancer compared to patients with no cancer." (PMID 38429330, 2024). "Although patterns of AChE forms were not affected by cancer, a decrease in the total activity of AChE in both molecular forms was observed." (PMID 37760598, 2023). "A potential example of a mechanism relevant to both cancer and neurodegeneration is the non-enzymatic binding of AChE acting at an allosteric site on the nicotinic alpha-7 receptor." (PMID 36500605, 2022). "Another potential example of a mechanism relevant to both cancer and neurodegeneration is the non-classical, non-enzymatic binding of acetylcholinesterase (AChE) acting at an allosteric site on the nicotinic alpha-7 receptor." (PMID 34073579, 2021). "The present study suggests that the growth-suppressive effects of inhibition of the non-neuronal, cancer-cell-intrinsic AChE via indirect parasympahomimetic drugs do not translate into improved survival in PCa." (PMID 33357230, 2020). "AChE is able to reduce intestinal cell or stem cell differentiation, and inhibit signal transduction via PI3K/Akt pathway, which is the critical pathway in cancer stem cell maintenance." (PMID 25220382, 2014). "The potent antioxidant activity and significant inhibition of AChE and BChE by the DMF fraction and the inhibition of cell growth by the EAF and DMF fractions of C. religosa focus on its prospect of affording an efficient treatment for AD and cancer, respectively." (PMID 40535822, 2025). "Notably, Ad.AChE was not able to inhibit most cancer cell growth at low MOI level, such as MOI of 1 or 10, compared to the control adenovirus (Ad.vector)." (PMID 25220382, 2014). "However, we can hypothesize an opposite balance in which there is high AChE activity and low levels of ACh; therefore, the ACh effects could not take place, and the cancer progression and aggressiveness would have to slow down." (PMID 37760598, 2023). "In cancer, a decrease in AChE activity could be (but is not necessarily) due to a reduction in the synthesis of this protein, thus avoiding apoptosis; however, the question is: what is the role of the AChE in apoptosis?" (PMID 37760598, 2023). "On the other hand, the involvement of AChE in nonneuronal functions such as the regulation of cell proliferation, differentiation, and apoptosis has suggested that it might play a role in different types of cancers." (PMID 32503288, 2020). "However, there is no report on cancer therapy using AChE protein." (PMID 25220382, 2014). "However, no cancer therapy research using viral vector to deliver AChE has been reported." (PMID 25220382, 2014). "In addition to its conventional enzymatic role in hydrolyzing acetylcholine, AChE could have an effect in cancer, independent of cholinergic transmission, that involves a variety of potential functions such as cell adhesion, differentiation, regulation of apoptosis and proliferation." (PMID 28077796, 2017).
cancer (continued). "In addition, the involvement of AChE in non-neuronal functions, such as the regulation of cell proliferation, differentiation, and apoptosis, suggests that it might play an important role in the formation of a cancer and serve as a potential therapeutic target in cancer therapy." (PMID 36500605, 2022).